ARID1A (AT-rich interaction domain 1A)
Diseases named in the same sentence as ARID1A in open-access papers (continued):
Sharing a sentence is not in itself a finding about the gene and the disease.
breast carcinoma (continued). "In breast cancer, ARID1A is regarded as a tumor suppressor and cooperates with CEBPα to suppress cell proliferation and migration." (PMID 34804958, 2021). "ARID1A is a key neoplasm suppressor gene that cooperated with CEBPα inhibited UCA1 transcription in breast cancer." (PMID 33592583, 2021). "The low expression of ARID1A is associated with poor disease-free survival and overall survival of patients with luminal A or HER2-rich breast cancer." (PMID 34804958, 2021). "For example, ARID1A, as a candidate tumor-suppressor gene in breast cancer, inhibited the cell progress, which also increased the sensitivity of drug therapy." (PMID 33592583, 2021). "Immunohistochemical staining (IHC) was used to detect the expression of ARID1A protein in 119 human breast cancer tissues and 32 normal adjacent tissues." (PMID 33592583, 2021). "Furthermore, ARID1A expression suppressed the accumulation of DNA double-strand breaks caused by radiation and could rescue the loss of radio-resistance triggered by HuR inhibition in patients with breast cancer." (PMID 33592583, 2021). "In breast cancer, ARID1A determines breast luminal lineage fidelity and endocrine therapy sensitivity." (PMID 33741974, 2021). "These two events, i.e., ARID1A loss-of-function and activated PI3K/AKT signaling, are commonly observed in endocrine-resistant breast cancer cells." (PMID 33741974, 2021). "Consistently, our proteomic results showed the suppression of critical proteins in the PI3K-mediated AKT-pathway, such as PP2A, DUSP8, and ARID1A, which were simultaneously overexpressed in breast cancer cells treated with combined MPSE and IR." (PMID 34217266, 2021). "Although ARID1A has been known as a tumor suppressor, mRNA expression of ARID1A is still higher in breast cancer than in normal control." (PMID 34063990, 2021). "ARID1A not only exerts an antitumor effect such as cancer cell migration and invasion on breast cancer but also enhances the sensitivity of breast cancer cells to 5-fluorouracil (5-FU)." (PMID 34671561, 2021). "As for the breast cancer samples, the pathway module 8 contained several well-known driver mutations, including KRAS, APC, and ARID1A." (PMID 33819263, 2021). "Collectively, our study indicates that METTL8 up-regulated by YY1 in breast cancer plays an important role in cancer cell migration through the mRNA modification of ARID1A, resulting in the attenuation of its translation." (PMID 34063990, 2021). "ARID1A is a key protein in the basal cell transition of breast cancer, and it plays a pivotal role in ERα-induced gene transcription." (PMID 32365920, 2020). "Methods: in this study, we examined tissue samples from 215 HER-2+ breast cancer patients to investigate the value of ARID1A and ANXA1 protein levels in trastuzumab response prediction and patient outcome." (PMID 33276477, 2020). "A study showed that ARID1A promoter methylation led to decreased ARID1A expression in breast cancer." (PMID 32334542, 2020). "We next evaluated the effect of modulating HuR expression on ARID1A levels in two breast cancer cell lines—MDA-MB-231 and Hs578t." (PMID 31847141, 2019). "To assess a potential role of ARID1A in the radiation resistance conferred by HuR, we downregulated ARID1A in a panel of human breast cancer cell lines—MDA-MB-231, MDA-MB-468, and SUM159PT—and assessed their clonogenic survival potential." (PMID 31847141, 2019). "Our results indicate that HuR binds ARID1A mRNA, thereby increasing its stability in breast cancer cells." (PMID 31847141, 2019). "After quantifying band intensities and normalizing them to actin, we found a strong and significant correlation between the abundance of ARID1A and HuR, supporting our findings that HuR promotes ARID1A expression in breast cancer tumors." (PMID 31847141, 2019). "Altogether, these results further imply that ARID1A plays an important role in radioresistance in breast cancer cells via the HuR–ARID1A axis." (PMID 31847141, 2019).
breast carcinoma (continued). "In the present study, we investigated the ability of HuR to modulate ARID1A expression in breast cancer and its contribution to radioresistance." (PMID 31847141, 2019). "Taken together, our work shows that HuR and ARID1A form an important regulatory axis in radiation resistance that can be targeted to improve radiotherapy in breast cancer patients." (PMID 31847141, 2019). "A The Cancer Genome Atlas (TCGA) study shows that mRNA levels of HuR and ARID1A are found to be elevated in breast cancer patients." (PMID 31847141, 2019). "This study identifies ARID1A as a novel HuR target and provides evidence for a pivotal role of the HuR/ARID1A axis in breast cancer radioresistance, thereby supporting the potential therapeutic targeting to enhance radiotherapy in breast cancer." (PMID 31847141, 2019). "These DEF values indicate that inhibition of ARID1A confers radiosensitization to the breast cancer cells." (PMID 31847141, 2019). "We found that the probability of disease-free survival was severely reduced in patients expressing high levels of HuR and ARID1A, highlighting the clinical role of the HuR–ARID1A axis in patients with breast cancer." (PMID 31847141, 2019). "For this, we performed disease-free survival curve analysis on breast cancer patients expressing high levels of both HuR and ARID1A." (PMID 31847141, 2019). "Accordingly, our data showed that the endogenous mRNA levels of ARID1A are negatively correlated with paclitaxel IC50 concentrations in tested breast cancer cells." (PMID 29392887, 2018). "We further evaluated the prognostic significance of ARID1A in breast cancer patients who received paclitaxel‐based chemotherapy." (PMID 29392887, 2018). "From the SurvExpress database, the prognostic value of low ARID1A mRNA expression was significantly correlated with poor RFS rates in 1901 breast cancer patients." (PMID 29392887, 2018). "Similar results were also observed in different ARID1A probes within the K‐M Plotter database against breast cancer patients." (PMID 29392887, 2018). "Particularly in breast cancer, ARID1A down‐regulation was highly correlated with cancer progression, for example, metastasis and recurrence." (PMID 29392887, 2018). "In present study, we screened the expression status of ARID1A and HIST1H2BE (H2B encoding gene) by Oncomine database and then examined the protein expression of ARID1A and histone H2B simultaneously on tissue microarray of breast cancer." (PMID 26904685, 2016). "Tissue microarray of breast cancer was used for examination of ARID1A and H2B expression by immunohistochemistry." (PMID 26904685, 2016). "To clarify the possible relation of ARID1A and H2B, we analyzed the expressing status of ARID1A and H2B on breast cancer." (PMID 26904685, 2016). "The goal of the study is to evaluate expressing status of ARID1A and H2B as well as their correlation on breast cancer." (PMID 26904685, 2016). "Here, we examined ARID1A protein expression in 75 cases of breast cancer and corresponding normal epithelium." (PMID 26904685, 2016). "It suggested that the expression of ARID1A is often companied by the high expression of histone H2B in a subset of breast cancers." (PMID 26904685, 2016). "In fact, Inoue and colleagues showed that re-expression of ARID1A in a breast cancer cell line augments transcriptional activation through glucocorticoid receptors, estrogen receptor, and androgen receptor." (PMID 24622842, 2014). "Several cancer-associated chromatin remodeling factors other than BAF155 have already been identified in breast cancer; for example, ARID1A, ARID1B, SMARCD1, PBRM1, BAF60A and BRG1." (PMID 25927994, 2014).
breast carcinoma (continued). "ARID1A mutations are observed in various tumors, including ovarian clear cell (OCCC) and endometrioid carcinomas, endometrial, and breast carcinomas." (PMID 24979463, 2014). "We have previously reported that ARID1A mRNA and protein expression is decreased in 56% of breast cancer tissues." (PMID 23349767, 2013). "Functional studies of ARID1A gene have proven that it’s a bona fide tumor suppressor gene both in breast cancer and other types of cancers." (PMID 23349767, 2013). "So, our results are in line with the observation in breast cancer cells after ARID1A KD." (PMID 41049615, 2025). "Furthermore, the study showed that low ARID1A expression breast cancer patients who received radiation therapy (RT) had higher expression of IL‐6 compared to patients with high ARID1A expression." (PMID 39779467, 2025). "ARID1A and ARID1B in the BAF subfamily are frequently mutated in breast cancer." (PMID 41278204, 2025). "Many pathogenic gene mutations common to breast cancer, such as Pten, Brca2, Atm, Cdh1, Chek2, Nf1, Arid1a, Pik3ca, and Esr1, revealed no alterations between NT2.5 and NT2.5-LM." (PMID 38717519, 2024). "In addition, ARID1A deletion activates ANXA1 protein expression in HER2+ breast cancer cells, which consequently induces resistance to trastuzumab through activation of AKT protein." (PMID 39697230, 2024). "Furthermore, the knockdown of ARID1A in hepatocellular carcinoma and breast cancer cells significantly enhanced cell invasion and migration." (PMID 39697230, 2024). "In addition, it was found that down-regulation of the ARID1A gene in gastric and breast cancer cells significantly enhanced cell proliferation." (PMID 39697230, 2024). "Therefore, wild-type ARID1A has been shown to correlate with improved clinical outcomes in ER+ breast cancer patients." (PMID 38893181, 2024). "In the SWI/SNF chromatin remodelling complex, a mutated AT-rich interaction domain 1A (ARID1A) subunit is enriched in metastatic ERα-positive breast cancers which are no longer responsive to endocrine therapy." (PMID 39282472, 2024). "In the patients with HER2-low breast cancer, patients with homologous recombination related genes (HRRGs) defects had an HRD score about twice that of those without related genes mutations, and were at higher risk of acquiring ARID1A, ATM, and BRCA2 mutations." (PMID 38366907, 2024). "Furthermore, in breast cancer, ARID1A has been reported to inhibit the expression of another long non‐coding RNA (lncRNA) called UCA1." (PMID 38041544, 2023). "In luminal A breast cancer, ARID1A downregulation induces EMT, suggesting that it may be a target in ER-positive breast cancer." (PMID 37173914, 2023). "Recently, another study found that the downregulation of ARID1A could accelerate EMT in luminal breast cancer." (PMID 37173914, 2023). "Within the 7 breast cancer cases, two cases showed a BRCA2 nonsense variant (p.R2318* and p.K3326*), one case showed ERBB3 G234R, one case showed KRAS G12V, and one case showed ARID1A P453fs." (PMID 36125633, 2023).
breast carcinoma (continued). "Further analysis of breast cancer patients with different molecular subtypes revealed that ARID1A expression was significantly lower in eMDSCshigh luminal A breast cancer (p = 0.0369), rather than in the luminal B, HER2 and Basal-like subtype (p = 0.0917, p = 0.4872, p = 0.3361)." (PMID 36329699, 2022). "Moreover, significant changes of EMT-related genes were detected in luminal A breast cancer cells after co-cultured with eMDSCs or ARID1A knock-down and overexpression of ARID1A significantly reversed this procedure." (PMID 36329699, 2022). "The cancer genome panel identified mutations in AT-rich interaction domain 1A(ARID1A)and breast cancer susceptibility gene 2 (BRCA2), but there were no available clinical trials or recommended drugs." (PMID 36426335, 2022). "The eMDSCs-ARID1A axis was essential for luminal A type of breast cancer metastasis and could be a potential target for metastatic breast cancer therapies." (PMID 36329699, 2022). "In addition, the high level of ARID1A is found in paclitaxel-sensitive breast cancer cells, whereas its lower level is found in paclitaxel-resistant cells." (PMID 35069887, 2022). "Furthermore, a study which focused on decreased ARID1A expression in breast cancer demonstrated that histone modification and promoter hypermethylation are the main causes of ARID1A gene expression loss." (PMID 35611248, 2022). "Indeed ARID1A deletion makes breast cancer cells sensitive to bromodomain and extraterminal domain (BET) inhibitors and HDAC inhibitors." (PMID 34804958, 2021). "BAF members are differentially impaired depending on the cancer type, with ER+ breast cancer primarily characterized by aberrations in the AT rich interactive domain 1A (ARID1A/BAF250A) subunit (~ 5% at the primary tumor and ~ 12% in resistant/metastatic setting)." (PMID 33284960, 2021). "ARID1A expression was higher in breast cancer than in the normal." (PMID 34063990, 2021). "Mutations in ARID1A are frequent in non-small cell lung cancer, colon cancer, bladder cancer and breast cancer, whereas mutations in KEAP1 and STK11 was predominate in non-small cell lung cancer (8.62% and 11.75%, respectively)." (PMID 34302033, 2021). "Furthermore, we showed how METTL8 affects the phenotype of breast cancer cells by identifying ARID1A as a target gene for METTL8." (PMID 34063990, 2021). "In addition, ARID1A loss or downregulation drives paclitaxel resistance and HER2/PI3K/mTOR-targeting drug resistance in breast cancer." (PMID 34804958, 2021). "To investigate whether METTL8 interacts with ARID1A mRNA in breast cancer cells, we performed an RNA immunoprecipitation assay (RIP)." (PMID 34063990, 2021). "Interestingly, the ARID1A gene expressions in four breast cancer cell lines were higher than the normal cell line." (PMID 34063990, 2021). "We then finally chose ARID1A based on the discrepancy between the expression level of mRNA and protein in breast cancer and canine mammary tumor databases because the function of METTL8 is mRNA methylation, which is known to result in restrained protein expression." (PMID 34063990, 2021). "Furthermore, in ER+ breast cancer, ARID1A was found to participate in the maintenance of luminal identity by modulating cellular plasticity." (PMID 34804958, 2021). "Many studies showed ARID1A served a function of tumor suppressor in breast cancer." (PMID 33592583, 2021). "Together, these results suggest that the interaction between ERα and ARID1A may provide an effective platform for maintaining the endocrine therapeutic response in ERα-positive breast cancer." (PMID 32365920, 2020).
breast carcinoma (continued). "HuR-induced expression of ARID1A is essential to reduce the levels of DNA fragmentation during radiation, expanding our understanding of the mechanisms by which HuR promotes radioresistance in breast cancer." (PMID 31847141, 2019). "However, when analyzing all patients with breast cancer, a moderate and significant correlation between ARID1A and HuR expression levels was observed." (PMID 31847141, 2019). "Mutation in ARID1A is not that frequent in breast cancer (only ∼5%) and there has been no reported association with ER status." (PMID 30057548, 2018). "Therefore, the aims of this study were to evaluate the effect of the ARID1A gene on breast cancer following paclitaxel treatment and to investigate the possible mechanism." (PMID 29392887, 2018). "The results suggest that ARID1A may be used to predict the outcome in breast cancer patients receiving paclitaxel‐based chemotherapy." (PMID 29392887, 2018). "Furthermore, ARID1A expression was down‐regulated in breast cancer tissue compared to normal tissues." (PMID 29392887, 2018). "In addition, we analysed ARID1A expression in breast cancer patients receiving paclitaxel‐based chemotherapy." (PMID 29392887, 2018). "There were 15 cases (20%) of breast cancers that were positive for ARID1A." (PMID 26904685, 2016). "Only 15 cases (20%) of breast cancers were positively expressed for ARID1A." (PMID 26904685, 2016). "The coexpression of ARID1A and H2B suggested that ARID1A may be involved in the histone modification in some subtypes of breast cancer." (PMID 26904685, 2016). "Decreased expression of ARID1A on breast cancer has been found in several studies." (PMID 26904685, 2016). "The expression of ARID1A was found in 20% cases of breast cancer." (PMID 26904685, 2016). "Our results indicate that ARID1A gene may be involved in carcinogenesis of some subtypes of breast cancer." (PMID 26904685, 2016). "However, Sausen and colleagues recently found that ARID1A or ARID1B mutations associate with worse OS in patients with neuroblastoma, and a previous breast cancer study noted that decreased ARID1A expression can confer worse prognosis." (PMID 24622842, 2014). "For example, nearly 60% of breast cancers demonstrate low to no ARID1A expression, while 2.0% [1.7%] of breast cancers showed ARID1A mutations." (PMID 25774356, 2014). "Copy number loss is not the main reason of ARID1A gene low expression yet in our current breast cancer research." (PMID 23349767, 2013). "ARID1A gene haploinsufficiency has been reported in breast cancer recently." (PMID 23349767, 2013). "Our observation is in agreement with a series of studies revealing that ARID1A expression is frequently lost or reduced in a number of cancer tissues and cell lines, such as breast cancer, uterine endometrioid carcinoma, ovarian clear cell and endometrioid carcinoma [13,18,20, and 21]." (PMID 22808142, 2012). "Notably, phosphorylation at S363 and S1184 was significantly upregulated in breast cancer, suggesting tumour-specific hyperphosphorylation that may disrupt ARID1A tumour-suppressive function and contribute to endocrine resistance." (PMID 41572083, 2026). "Despite the tumour suppressive role of ARID1A and loss of BRG1 activity in ARID1A-perturbed ER+ breast cancers, BRG1 and BRM may present as efficient targets in other subtypes due to their crucial roles in promoting progression and mediating resistance to chemotherapy." (PMID 41278204, 2025). "Moreover, we found that eMDSCs suppress the ARID1A expression to promote EMT in luminal A breast cancer cells, which might provide a new light on developing novel treatment regimens for relapsed luminal A breast cancer after conventional therapies." (PMID 36329699, 2022).